IL33 (interleukin 33)
Diseases named in the same sentence as IL33 in open-access papers (continued):
Sharing a sentence is not in itself a finding about the gene and the disease.
asthma (continued). "As IL33 is an important asthma susceptibility gene, this effect of IL-33 on HRV infection of MCs highlights a potential gene-environment interaction that contributes to virus-induced asthma exacerbations." (PMID 36366528, 2022). "We replicated the association of a previously reported rare variant in IL33 with asthma risk and found significant enrichment of rare variant burden in candidate genes from common variant allergic disease loci." (PMID 35368043, 2022). "As an ”alarmin” and strong inducer of Th2 immune responses, IL-33 is implicated in Th2-mediated allergic inflammatory disorders, such as asthma." (PMID 34531552, 2022). "Further, our sensitivity results show that the gene-based association between IL33 and asthma is driven by low frequency variants (MAF <5%) which we had no power to detect associations with individually." (PMID 36685501, 2022). "Using children from a well described bronchiolitis cohort and their controls that collected detailed phenotype and clinical data at school-age, we were able to detect a nominal association with asthma for the gene IL33." (PMID 36685501, 2022). "Associations between rs1888909 (T) allele copies and increased IL33 mRNA and IL-33 protein levels further suggests that this regulatory variant mediates the development of asthma among individuals carrying this risk allele." (PMID 34675193, 2021). "In CD4+ T cells, the IL-33/ST2 signaling pathway plays an important role in Th2 activation, and interestingly, IL1RL1 variants are linked to increased risk of IL-33-driven type 2 inflammation in asthma." (PMID 33924911, 2021). "Rhinovirus induces IL-33-dependent type 2 asthma exacerbations, and rhinovirus-induced DNA methylation changes on many genes are linked with asthma, especially the substantial changes seen on gene SMAD3." (PMID 34566492, 2021). "Genetic studies have identified a large number of genes associated with asthma and its phenotypes, including IL-33 and its receptor." (PMID 34608100, 2021). "Although, several other polymorphisms within the IL-33 gene have been shown to be significantly associated with asthma susceptibility in various populations." (PMID 34177886, 2021). "Activation of airway epithelium with allergens including Alt extract often causes severe asthma attacks and results in the release of several alarmins including IL-33, IL-25, GM-CSF, TSLP which orchestrate the downstream type 2 immune response." (PMID 34484177, 2021). "The single-nucleotide polymorphisms (SNPs) associated with increased asthma risk at the IL33 GWAS locus reside within a linkage disequilibrium (LD) block in a noncoding genomic segment located 2.3 kb upstream of the IL33 gene." (PMID 34675193, 2021). "Here, we combine genetic fine-mapping using GWAS datasets with functional annotations from relevant tissues to characterize the asthma-associated region upstream of the IL33 gene." (PMID 34675193, 2021). "To simplify the role of leptin in the IL-33-induced asthma model, we used leptin-deficient ob/ob mice." (PMID 34074279, 2021). "Variants at the IL33 locus have been robustly associated with asthma in GWAS of ethnically diverse populations." (PMID 34675193, 2021). "In humans, genome-wide association studies have associated asthma risk with variants in or near il-33 and st2 loci." (PMID 34960788, 2021). "Genetics can also detect targeted genetic variants with protective functions, such as a genetic variant in IL33, one of the common genes of asthma and AR." (PMID 34946955, 2021). "Expression of Il33 or Il1rl1 genes also correlates with susceptibility to asthma, as well as the type 2 response in murine experimental asthma models, further supporting a crucial role of IL-33-mediated ILC2s activation during allergy." (PMID 34194431, 2021). "The purpose of this study was to elucidate the pathogenesis of obesity-associated asthma by focusing on the interaction between leptin and IL-33." (PMID 34074279, 2021).
asthma (continued). "GWAS have reproducibly found that genetic variations in IL-33 and IL1RL1 genes alter IL-33/IL-1RL1 pathway through different molecular changes in gene transcription or protein synthesis, and correlate with increased asthma susceptibility." (PMID 33925009, 2021). "Recent studies revealed that cytokines such as thymic stromal lymphopoietin (TSLP), IL-33, and IL-25, highly expressed in the airway epithelium, are implicated in human asthma." (PMID 33445787, 2021). "For this, we used a human Bacterial Artificial Chromosome (BAC; clone RP11-725F15), approximately 166 kb long, spanning the coding region of the IL33 gene and its upstream sequences, including the 20 kb asthma-associated region." (PMID 34675193, 2021). "Recent studies have also implicated IL-33 in virus-induced asthma exacerbations by driving type 2 immune responses, which is enhanced in human asthmatic patients." (PMID 34960788, 2021). "IL-33 expression in the neonatal lung can be increased by various respiratory insults associated with asthma development." (PMID 34048460, 2021). "We found that the 5 kb asthma-associated region is able to physically interact with the IL33 promoter in both cell types." (PMID 34675193, 2021). "Significant associations between genetic variants of IL33 and IL1RL1 and human asthma have consistently been identified in several genetic studies, suggesting that the IL-33/ST2-axis is likely to play a role in the disease." (PMID 33255348, 2020). "Lastly, several studies have linked polymorphisms in epithelial alarmins TSLP and IL33 with the risk for asthma." (PMID 33255348, 2020). "Being one of the major upstream regulators of type 2 inflammation, IL‐33 has been linked to both asthma and allergic inflammation." (PMID 33133517, 2020). "IL-33 has been associated with several chronic diseases such as asthma, atopic dermatitis, and inflammatory allergy, and recently, it was discovered that it plays important roles in regulatory immune responses." (PMID 32971846, 2020). "In agreement with other reports, we show that the asthma risk haplotype leads to enhanced NF-κB activity after IL-33–mediated IL1RL1 signaling in a reductionist cell model." (PMID 32324168, 2020). "Region 9p24 also belongs to one of the most replicated asthma loci, associating with the IL‐33 gene." (PMID 33133517, 2020). "IL-33 is an innate cytokine commonly found in the airways to be associated with asthma, and has been shown to be involved in group 2 innate lymphoid cell (ILC2) development and airway remodeling with steroid resistance." (PMID 33324573, 2020). "As the IL-33 pathway is strongly implicated in human asthma, HpARI, with its unique mechanism of action and strong binding to IL-33, is a potential therapeutic agent." (PMID 32695116, 2020). "Extensive studies have analyzed the functional roles of IL-33 in type 2 immunity-associated allergic responses and diseases such as asthma." (PMID 32903501, 2020). "The gene that encodes IL‐33 is separately implicated in the genetic etiology of asthma through the fifth most replicated locus on chromosome 9p24." (PMID 33133517, 2020). "Whereas a number of studies have examined the disease-associated functions of IL-33, including in asthma, allergy, anaphylaxis, cardiovascular disease, and the nervous system, few studies have focused on the role of IL-33 in bone metabolism." (PMID 32046264, 2020). "Epithelial-derived cytokines such as thymic stromal lymphopoietin (TSLP), IL-25 and IL-33 are important factors in the pathogenesis of asthma as they promote Th2-associated immune responses via activation of DCs." (PMID 32477356, 2020). "Single nucleotide polymorphisms in the IL-33 gene cause a predisposition to the development of asthma." (PMID 31057533, 2019). "It has been shown that IL-33 promotes lung fibrosis and bronchial remodeling, causing further advancement of asthma." (PMID 31057533, 2019).
asthma (continued). "Several genome wide association studies have found SNPs in genes encoding IL-33 to be risk factors for asthma." (PMID 31490928, 2019). "In contrast, obese asthma in adults is associated with increased airway and systemic inflammation, consistent with our observations of increased TNFα, IL-5, IL-33 and leptin concentrations in the BALF of dams fed the high fat diet." (PMID 30700289, 2019). "AAL(S) was shown to reduce the severity in asthma mice models by suppressing inflammation, mucus-secreting cell numbers, type 2-associated cytokines (IL-33, IL-5 and IL-13), serum IgE and airway hyper-responsiveness." (PMID 31623614, 2019). "Polymorphisms in the il1rl1 or il33 genes are found in patients suffering from exacerbated type 2 immune responses, notably severe atopic dermatitis and asthma, illustrating the important role of these genes in the susceptibility to allergic diseases." (PMID 30949175, 2019). "What is very interesting, and highlights the role of IL-33 in the development of asthma, is a rare loss of function mutation (rs146587587-C), in which premature STOP codon causes truncation of the last 66 amino acids of the cytokine." (PMID 31057533, 2019). "The locus on chromosome 19 harbors Il33 and is syntenic to association signals observed for asthma at the IL33 locus in humans." (PMID 31869344, 2019). "Interleukin-33 is released in the airways following acute ozone exposure and has the ability to cause airway hyperresponsiveness, a defining feature of asthma." (PMID 31455422, 2019). "The chromosome 19 locus harbors Il33 and is syntenic to asthma association signals observed at the IL33 locus in humans." (PMID 31869344, 2019). "These include GWAS studies revealing several genes essential in ILC2 biology as susceptibility markers for human asthma such as the ILC2-activating alarmin IL-33 and its cognate receptor ST2 (IL1RL1) as well as the transcription factors GATA3 and RORα." (PMID 31231357, 2019). "The loci for IL1RL1 (ST2 gene) and IL-33 contains a single nucleotide polymorphism that was associated with asthma in a large-scale genome-wide association study." (PMID 31191511, 2019). "In large-scale genome-wide association studies, genes encoding IL-33 and its receptors have been identified as susceptibility loci in asthma.The alarmin activities of IL-33 are regulated at multiple levels." (PMID 30886621, 2019). "As a major finding of these projects, asthma onset has been associated with a number of genes coding for HLA, IL-13, IL-33, thymic stromal lymphopoietin [TSLP], IL-1 receptor-like 1 [IL-1RL1], ST2, and the receptor for IL-33." (PMID 29992143, 2018). "To illustrate the role of PTRF in IL-33 release and asthma development, we use PTRF+/− mice to show that loss of PTRF led to a greater airway hyper-reaction, with an intense airway inflammation and potent type 2 immune responses." (PMID 29977243, 2018). "The impact of genetic variants of IL-33 and its receptors on the risk of asthma and/or allergy in humans was investigated." (PMID 30304837, 2018). "It is plausible to consider IL-33 as a potential routine biomarker for diseases associated with a cell damage like asthma, COPD, AD, RA, and heart failure." (PMID 29713240, 2018). "We found that the rare splice-disrupting PTV rs146597587 in IL33 is associated with protection against asthma (MAF = 0.48%, p = 7.6 × 10−13, OR = 0.64, 95% confidence interval (CI): 0.57–0.72)." (PMID 29691392, 2018). "In particular, IL-33 significantly contributes to pathogenesis of allergy and asthma; genetic variations in the IL33 locus are associated with increased susceptibility to asthma." (PMID 30257479, 2018). "IL-33 causes eosinophilic inflammation and Th2 cytokine production in the lungs and is involved in arising asthma." (PMID 30176857, 2018). "It has also been shown that increased IL-33 expression is associated with enhanced reticular basement membrane thickness in endobronchial tissues in children with severe therapy-resistant asthma." (PMID 30233590, 2018).
asthma (continued). "Of all known SNPs associated with asthma and allergic disease, rs4742170 is the only one to be located in a putative regulatory area of the IL33 gene that is associated with binding of transcription factors relevant to the progression of airway pathologies." (PMID 30544846, 2018). "It has been shown that many of the single nucleotide polymorphisms (SNPs) in the human IL-33 gene associated with asthma are located in the promoter and intron 1, both of which are important for gene expression." (PMID 30233590, 2018). "A study aiming to identify the association of IL-33 polymorphisms with wheezing phenotypes of asthma identified that rs4742170 and rs7037276 are associated with intermediate-onset wheeze, and rs1342326 is associated with persistent wheeze." (PMID 29987222, 2018). "CREB1 binding to a site in the IL33 promoter created by the rs928413(G) allele is consistent with the observation of more pronounced clinical asthma symptoms in patients carrying both homozygous and heterozygous rs928413(G) variants." (PMID 30257479, 2018). "IL-33 has been extensively characterized as functionally important in Th2-associated inflammatory diseases including asthma, atopic dermatitis and helminth infections." (PMID 29587772, 2018). "Large-scale genome-wide association studies demonstrated that IL33 locus includes several single-nucleotide polymorphisms (SNPs) associated with asthma development in different populations." (PMID 30257479, 2018). "IL33 is known to promote allergen-driven eosinophil-associated airways inflammation in rodents and IL33 polymorphisms are associated with wheezing, asthma, and atopy in humans." (PMID 30150981, 2018). "Asthma is associated with variants in the genes encoding IL-33 and its receptor ST2 (also known as ST2L and IL1RL1)." (PMID 30174671, 2018). "Mast cells are major effectors of allergy and asthma, and can be activated by the alarmin IL-33, which is linked to allergic disease." (PMID 30619366, 2018). "In our previous study we revealed a possible molecular mechanism underlying the association between SNP rs928413 in the IL33 promoter and elevated risk of asthma progression." (PMID 30544846, 2018). "Genes such as HLA, IL13, IL33, thymic stromal lymphopoietin (TSLP) involved in Th2 pathway, IL-1 receptor–like 1 (IL1RL1), encodes ST2, and the receptor for IL-33 are associated with asthma onset." (PMID 29904594, 2018). "This review summarizes current findings regarding IL-33 and discusses its pathogenic role in allergic diseases including asthma, allergic rhinitis (AR), chronic rhinosinusitis (CRS), atopic dermatitis (AD), food allergy (FA), allergic keratoconjunctivitis." (PMID 29987222, 2018). "Increasing genomewide association studies have reported the loci of IL-33 gene plays important roles in susceptibility of several diseases such as asthma and allergic rhinitis." (PMID 29987222, 2018). "More specifically, increased expression of IL-33 are associated with increased reticular basement membrane thickness in endobronchial specimens from children with severe therapy-resistant asthma." (PMID 29987222, 2018). "We replicated an association between a rare interleukin 33 (IL33) splice site variation and eosinophil count and asthma risk, and showed that it also associates with hay fever risk." (PMID 28787443, 2017). "Due to the effect of IL-33 in the inflammatory process, other polymorphisms in this gene have been associated with asthma, inflammatory bowel disease and Alzheimer’s disease." (PMID 28045954, 2017). "Epithelial cell-derived cytokines, including thymic stromal lymphopoietin (TSLP), IL-25, and IL-33 are critical regulators of innate and adaptive immune responses associated with Th2 cytokine-mediated inflammation in asthma." (PMID 28199345, 2017). "We report a rare variant, rs146597587, in IL33 representing a loss-of-function mutation in this known asthma gene." (PMID 28273074, 2017).
asthma (continued). "Specifically, in pediatric severe asthma, we have shown increased expression of the innate epithelial cytokine IL-33 in the bronchial tissue and an association with increased levels and both airway remodeling and steroid resistance." (PMID 28725641, 2017). "An enriched presentation of IL-33/ILC2 axis-directed Th2 cytokines in CRS nasal tissue leads to a rapid decline in lung function associated with poor asthma control." (PMID 28199345, 2017). "The identification of IL-33 and its receptor as asthma susceptibility genes has opened up a fruitful new field of study that has exponentially increased our understanding of the mechanisms driving aberrant type-2 immune responses." (PMID 28721208, 2017). "The IL33 splice acceptor mutation protects against asthma (OR = 0.47; 95% CI: 0.32–0.70, P = 1.8×10–4)." (PMID 28273074, 2017). "In the UK Biobank, we found that the rare C-allele at IL33-rs146597587 associated with reduced eosinophil count is also associated with lower risk of asthma (P = 2.60x10-7, odds ratio = 0.56) and allergic rhinitis (P = 4.21x10-4, odds ratio = 0.55)." (PMID 28787443, 2017). "Association between IL33-rs146597587 and asthma, allergic rhinitis, or endometriosis risk in the UK Biobank." (PMID 28787443, 2017). "The association between IL1RL1 and IL33 variants and asthma risk is well established and has been replicated in ethnically diverse populations, and in severe forms of adult asthma and in particular with early childhood asthma with exacerbations." (PMID 28273074, 2017). "Once the eosinophil count association of the splice acceptor variant was established, we assessed its effect on asthma, based on the prior association of IL33 and with asthma risk and the role of eosinophils in the pathogenesis of asthma." (PMID 28273074, 2017). "Through GWAS, we previously discovered common sequence variants in IL1RL1 and IL33 that associate strongly with blood eosinophil counts and risk of asthma, consistent with the link between eosinophilic inflammation and asthma." (PMID 28273074, 2017). "Associations of the IL33 splice acceptor variant rs146597587[C] with eosinophil counts and asthma in Iceland and abroad." (PMID 28273074, 2017). "Here we demonstrate that viral-induced HDM-asthma exacerbations associate with increased lung expression of three upstream cytokines whereas IL-33 and TSLP were also induced by HDM alone although to a lesser extent." (PMID 26879906, 2016). "IL-33 is over-expressed in the lungs of patients with idiopathic pulmonary fibrosis, asthma, and lung inflammation, and the over-expression of IL-33 is associated with ILC2 expansion." (PMID 27547445, 2016). "The ST2/IL-33 axis has been associated with pathological diseases including asthma, rheumatoid arthritis, atherosclerosis and GVHD." (PMID 26735493, 2016). "Bronchial smooth muscle cells (BSMCs) from severe asthmatics have been shown to overexpress the Th2-driving and asthma-associated cytokine IL-33." (PMID 26318341, 2015). "Interleukin-33 is considered to be linked to the development of several allergic diseases such as asthma and atopic dermatitis." (PMID 26425339, 2015). "IL-33 is an alarmin cytokine suggested by genetic association and functional studies to play an important role in inflammatory diseases such as asthma." (PMID 26365875, 2015). "Specifically, IL33 was significantly associated with asthma in Latino children using the ensemble learning gene-based test, but this gene was of borderline significance using the other 2 approaches." (PMID 26619286, 2015). "Further support of this role comes from murine models and large-scale genome-wide association studies in which asthma-susceptibility loci have been identified in the regions for IL33 and the cognate receptor for IL-33, IL1RL1 (i.e. ST2)." (PMID 26318341, 2015). "GWAS studies have shown that rs1342326, rs3939286, and rs2381416 SNPs within IL33 seem to be an asthma-susceptibility gene." (PMID 24779919, 2014).